ABCC5 (ATP binding cassette subfamily C member 5)
Diseases named in the same sentence as ABCC5 in open-access papers (continued):
Sharing a sentence is not in itself a finding about the gene and the disease.
cancer (continued). "By performing survival analysis on clinical data of 23 types of cancer patients in the database, researchers found that the expression of ABCC5 affected the survival rate of testicular cancer patients aged 30–40 years." (PMID 39563862, 2024). "Inhibition of ABCC5 expression enhances the anti-cancer activity of sorafenib, underscoring the potential therapeutic significance of targeting ABCC5 to overcome sorafenib resistance in HCC." (PMID 38562143, 2024). "Given that ABCC5 is regulated by several pathways in a broad range of cancer types, it is a prospective target for cancer treatment." (PMID 39563862, 2024). "Numerous studies have demonstrated that ABCC5 exhibits increased expression in a variety of cancers." (PMID 39563862, 2024). "ABCC5 mediates drug resistance and promotes tumour proliferation and metastasis in different types of cancer." (PMID 39563862, 2024). "Of note, some of the identified drugs are anti-cancer agents that inhibit RNA formation, such as floxuridine, oxaliplatin, and cisplatin, which are related to ABCC5 and GALNT14." (PMID 37478211, 2023). "Amongst the nine primary transporters (ABCC1-6, ABCC10-12, or MRP 1-9) in the ABCC family, ABCC5 was found to transport nucleoside monophosphate analogues and produce cancer drug resistance." (PMID 35141332, 2022). "The mRNA of STATH, RIC8A, and ABCC5 levels were downregulated in cancer samples in comparison to the control samples." (PMID 35992817, 2022). "Additional putative targets of miR-129-5p that are associated with drug resistance in cancers are ABC transporters (ABCB1, ABCC5, ABCG1) and RUNX1." (PMID 34063443, 2021). "Current studies on ABCC5 have mainly focused on the impact of its transmembrane protein transport function on the efficacy of cancer chemotherapy." (PMID 33994848, 2021). "Elevated expression of genes such as ABCC5, LRFN1, ELOVL6, and HTR2B have been associated with metastasis in other cancer types." (PMID 34680307, 2021). "For example, ABCC5, one member of the ABC superfamily, is a multidrug-resistance-associated protein 5, which is related to the drug efflux of multidrug resistance of cancer cells." (PMID 28077793, 2017). "Although ABC transporter genes including ABCC5 have been studied in relation to cancer treatment and drug resistance, little is known about ABCC5 in relation to T2D." (PMID 25117150, 2014). "However, this review emphasises caution in targeting ABCC5 for cancer therapy due to its underappreciated physiological function(s), particularly in the brain and male reproductive system." (PMID 41009771, 2025). "This research further investigates ABCC5 co-expression patterns, functional pathways, immune infiltration, mutation types, and methylation in HCC, assessing its potential in diagnosis, monitoring, and as a target for anti-cancer therapies." (PMID 40860808, 2025). "Importantly, the study reports the synthesis of peptide inhibitors with the potential to treat ABCC5-driven drug resistance in cancer patients." (PMID 40593462, 2025). "Third, drug tolerance and drug-drug interactions: Cancer cells may compensate for the inhibitory effects of ABCC5 through other resistance mechanisms, and the developed inhibitors may face rapidly emerging drug tolerance." (PMID 39563862, 2024). "Additionally, we will discuss ABCC5’s potential as a therapeutic target for overcoming drug resistance in cancer treatment." (PMID 39563862, 2024). "In conclusion, ABCC5 is a very promising target for cancer therapy, and drug resistance in cancer therapy may be overcome or reduced with inhibitors or other strategies against ABCC5." (PMID 39563862, 2024).
cancer (continued). "The C subfamily contains 13 members, of which the ABCC5 gene is upregulated in the expression of various cancers (such as breast, esophageal, head and neck, kidney, liver, and lung cancers) and has been confirmed to be related to cancer progression." (PMID 37351514, 2023). "Both ILVBL and ABCC5 genes did not form any edges in GTEx normal condition, which indicated that gaining the (ILVBL, LIMS2), (ILVBL, LIMS2), and (LIMS2, ABCC5) edges could be related to the formation of LUAD cancer." (PMID 35524179, 2022). "Our study suggests that the regulatory changes for ABCC5 and LIMS2 led to the correlation of these two genes only existed in LUAD, which could be associated with LUAD cancer etiology." (PMID 35524179, 2022). "This cancer-promoting effect of ABCC5 was also validated in our own samples." (PMID 33994848, 2021). "Based on previous studies showing that CDK1 can specifically phosphorylate AR at serine 81 to activate AR transcriptional activity, we hypothesize that the pro-cancer effect of ABCC5 is mediated by stabilizing CDK1 to activate AR phosphorylation." (PMID 33994848, 2021). "Multidrug resistance protein 5 (MRP5/ABCC5) was shown to confer resistance to the commonly used cancer drug 5-FU in human embryonic kidney cells in vitro, increasing the EC50 value by a factor of ten in cells transfected with MRP5 compared to non-transfected cells." (PMID 29743944, 2018). "Additionally, ABCC5 is downregulated by several microRNAs in multiple types of cancer 17, 21-23." (PMID 33994848, 2021). "In addition, siRNA-mediated silencing of all transcripts of eight genes that showed a consistent differential splicing signature across multiple cancer types (ABCC5, ANKHD1, DYNLL1, F8, RPL31, TMEM14C, UQCC, and CRNDE) failed to reveal differences in cell viability." (PMID 25424858, 2015). "Activation of NRF2 axis in cancer cells triggers the induction of multiple anti-ferroptotic genes, including SLC7A11, ATP binding cassette subfamily C member 5 (ABCC5), metallothionein 1G (MT1G), FSP1, CBS, and superoxide dismutase 2 (SOD2)." (PMID 39624080, 2024). "Despite P-gp expression was not correlated to oridonin resistance, our COMPARE analysis revealed that another member of ABC superfamily, i.e., ABCC5, was a molecular determinant to mediate resistance to oridonin in the NCI cancer cell line panel." (PMID 29713280, 2018). "ABCC5 is in the same family as the known drug efflux pump ABCC1/MRP1 and is thought to confer chemoresistance through reducing effective concentrations of chemotherapeutic drugs in cancer cells." (PMID 41009771, 2025). "However, ABCC5’s effects extend beyond these actions, working with other genes to regulate key molecules in the TME and affecting cancer cell behavior." (PMID 40860808, 2025). "Genes and AS events enrolled in the comprehensive prognostic signature included RHOT1 (ES), SH3KBP1 (AP), AGTRAP (AA), PACS2 (AP), RBPMS (AT), B3GNTL1 (AP), MOBP (AT), NPHP3 (ES), ABCC5 (RI), FKTN (ES) and FKBP8 (AA), many of which are known to play important roles in cancer biology." (PMID 32467664, 2020). "Additionally, we also observed an up-regulation in some cancer stem cell markers such as NANOG, ABCC2, ABCC5, CD44 and KLF450,51." (PMID 31597943, 2019). "Because kaempferol sensitizes OVCAR-3 cancer cells' response to cisplatin treatment, the effect on gene expression by cisplatin and/or kaempferol was further evaluated by analyzing mRNA levels of ABCC1, ABCC5, ABCC6, NFκB1, cMyc and CDKN1A genes." (PMID 20459793, 2010). "For cisplatin/kaempferol treatments on OVCAR-3 cancer cells, the mRNA levels of ABCC1, ABCC5, and NFkB1 did not change." (PMID 20459793, 2010).
tumor (37 papers, 2010 to 2025). "In HCC, missense mutations reveal the role of ABCC5 and its related genes in tumors, driving the development of targeted therapies to regulate the stability of tumor suppressor proteins or optimize existing treatment strategies." (PMID 40860808, 2025). "Many previous studies have shown that high expression of ABCC5 is closely associated with the development of drug resistance after tumor treatment 16-19, 22, 23, 30-32, 36-39." (PMID 33994848, 2021). "The G allele of the intronic rs939338 in the ABCC5 gene was reported to be associated with worse 5-year event-free survival in two cohorts, including data obtained from germline (alive patients) and tumor samples (dead patients)." (PMID 34572110, 2021). "Subsequent explorations revealed that ABCC5-based scores and Tumor stage could serve as independent risk factors for HCC prognosis." (PMID 40860808, 2025). "Furthermore, the overexpression of ABCC5 is strongly linked to the activation of Treg cells, which promotes immune evasion by tumor cells and accelerates tumor progression." (PMID 40860808, 2025). "ABCC5 has been highly associated with tumor cell resistance in previous studies 16, 19, 30-32." (PMID 33994848, 2021). "Furthermore, high expression of ABCC3 and ABCC5 in tumor biopsy samples is linked to a higher risk of death." (PMID 25605243, 2015). "Similarly, ABCC5 expression was also highly associated with tumor stage (p = 0.006)." (PMID 33994848, 2021). "Finally, two combinations of ABCC5 polymorphisms resulted in protection from this neoplasia." (PMID 27547186, 2016). "This study highlights the importance of co-expression networks in understanding complex diseases and how ABCC5 collaborates with other genes to modulate tumor progression." (PMID 40860808, 2025). "ABCC5 contributes to tumor cell proliferation, migration, and metastasis by activating related signaling pathways." (PMID 40860808, 2025). "ZDV therapeutic potential in HCC is closely related to its ability to modulate ABCC5 expression, influencing cellular responses to nucleoside-based drugs and potentially inhibiting tumor growth." (PMID 40860808, 2025). "Several of the newly identified interacting proteins, including ABCC5, have gained notoriety for their role in drug resistance and tumor cell survival under conditions of therapeutic stress." (PMID 40952239, 2025). "Studies suggest that ABCC5 promotes tumor cell immune escape by regulating the activity of immune cells within the TME, especially the proliferation of Treg cells, thereby exacerbating immune resistance in tumors." (PMID 40860808, 2025). "Individualized therapy: As the expression level of ABCC5 varies in different tumours and patients, conducting individualized therapy research is a key direction for the future." (PMID 39563862, 2024). "In multivariate analysis, ABCC5 index and extent of tumour resection were identified as factors with independent prognostic power." (PMID 39563862, 2024). "By detecting the level of ABCC5 expression in a patient’s tumour, a treatment plan can be tailored to the patient." (PMID 39563862, 2024). "Recent studies have indicated that ABCC5 expression increases abnormally in numerous malignant tumors, promoting tumor proliferation and metastasis." (PMID 35504877, 2022). "Although both tumor net weight and size decreased after ABCC5 knockdown or enzalutamide treatment alone, ABCC5 depletion combined with enzalutamide treatment showed a more significant inhibitory effect on xenograft tumor proliferation than enzalutamide alone." (PMID 35504877, 2022). "Functional assays indicated that ABCC5 depletion resensitized enzalutamide-resistant cells to inhibit cell growth and impeded xenograft tumor proliferation." (PMID 35504877, 2022). "Exosomal miR-128-3p is a tumor-suppressor miRNA that regulates ABCC5, which is a part of the ABC transporter family also known as MRP5." (PMID 35563246, 2022).
tumor (continued). "To further explore the relationship between ABCC5 overexpression and clinicopathological characteristics, we compared ABCC5 expression in different pathological scores and tumor stages." (PMID 33994848, 2021). "Then, we inhibited CDK1 kinase activity with the CDK1-specific inhibitor RO-3306 and found that the ability of highly expressed ABCC5 to promote tumor proliferation and migration was also inhibited when CDK1 kinase activity was inhibited." (PMID 33994848, 2021). "Consistent with the transcriptome results, we also found that ABCC5 was strongly overexpressed in the tumor tissue at the protein level compared with normal prostate tissue." (PMID 33994848, 2021). "The results showed that ABCC5 expression is significantly associated with the infiltration of B cells, CD4+ T cells, macrophages, neutrophils, and dendritic cells in the tumor microenvironment." (PMID 33994848, 2021). "FOXM1 and ABCC5 were consistently expressed in these same tumor tissues, although the clinical history of patients and their sensitivity to chemotherapeutic agents were unavailable." (PMID 28277541, 2017). "Further to investigate the potential role of tumor-intrinsic ABCC5 in promoting osteolytic lesion formation, we performed an in vitro osteoclast differentiation assay." (PMID 23174366, 2012). "We have previously shown that 5-fluorouracil treatment affects the expression profile of relevant cellular transporters including multidrug resistance proteins (MRPs), and that MRP5 (ABCC5) influences chemoresistance of these tumor cells." (PMID 24212609, 2010). "ABCC5 may induce drug resistance in tumor cells by regulating drug transport, thus impairing the effectiveness of chemotherapy." (PMID 40860808, 2025). "In summary, the copy number increase and deletion of ABCC5-based genes in patients with HCC led to missense mutations in the gene loci, resulting in errors in certain genes encoding proteins and contributing to the progression of tumor cells." (PMID 40860808, 2025). "The high expression of ABCC5 in HCC may promote tumor resistance by participating in immune microenvironment reprogramming, particularly through modulating immune cell infiltration." (PMID 40860808, 2025). "ABCC5 gene overexpression in tumours is correlated with chemotherapy resistance and poor prognosis." (PMID 41009771, 2025). "Therefore, high expression of ABCC5 exacerbates tumor progression and chemotherapy resistance by regulating RNA splicing, cell cycle signaling pathways, and immune escape mechanisms." (PMID 40860808, 2025). "High expression of ABCC5 may help tumor cells evade immune surveillance and drug inhibition by altering metabolic pathways or inducing mutations." (PMID 40860808, 2025). "Specifically, ABCC5 correlation with Tregs suggests that ABCC5 may modulate the tumor immune microenvironment, facilitating immune escape by promoting Tregs accumulation, which suppresses anti-tumor immune responses." (PMID 40860808, 2025). "Finally, individualized treatment plans should be formulated according to the expression of ABCC5 in patients' tumours, combined with gene detection and targeted therapy to optimize the therapeutic effect." (PMID 39563862, 2024). "Furthermore, immunofluorescence of tumor tissue also confirmed the high expression of ABCC5 in CRPC." (PMID 35504877, 2022). "Interestingly, the expression pattern of ABCC5 in individual tumours closely followed that of TYMP and TK1." (PMID 34132895, 2021). "FOXM1 and ABCC5 proteins in the tumor tissues were stained by immunohistochemistry." (PMID 28277541, 2017). "Tumor volumes decreased in the shABCC5 groups, whereas the shABCC5 plus enzalutamide treatment group showed a synergistic effect with dramatic tumor repression, indicating that the ABCC5 knockdown overcame enzalutamide resistance and restored the sensitivity of resistant cells to enzalutamide." (PMID 35504877, 2022).
tumor (continued). "However, the concrete biological mechanisms of ABCC5 in tumor progression and drug resistance remain unclear, especially the downstream regulatory pathway of ABCC5." (PMID 33994848, 2021). "This study, through the integration of multi-omics data, is the first to propose ABCC5 as a potential biomarker for HCC and reveals its roles in tumor progression, drug resistance, and immune evasion." (PMID 40860808, 2025). "It was observed in the TCGA database that ABCC1, ABCC4, ABCC5, and ABCC10 were significantly upregulated in tumor tissues, while ABCC6 and ABCC7 were downregulated in HCC tissues." (PMID 35342392, 2022). "AGTRAP1, ABCC5, SH3KBP1, and RBMX were upregulated, while PTGR1 was downregulated in tumor samples as compared to normal samples." (PMID 36338975, 2022). "This means that tumours with the highest expression of TYMP and TK1, which would result in high FdUMP levels, also had high ABCC5 expression, which would result in efflux of FdUMP." (PMID 34132895, 2021). "Further, it was reported that expression levels of ABCC3 and ABCC5 changed during tumor development, and the expression of ABCC3 was significantly correlated with high tumor grade." (PMID 31622355, 2019). "ABCC5 expression was low when FOXM1 expression was low in the same tumor tissue and the higher FOXM1 expression, the stronger was ABCC5 expression in the same tumor tissues." (PMID 28277541, 2017). "FOXM1 and the ABC transporter ABCC5 were consistently overexpressed in paclitaxel-resistant NPC cells and tumor tissues." (PMID 28277541, 2017). "After screening the gene expression of ABC transporters and FOX molecules, we found that FOXM1 and ABCC5 were consistently overexpressed in the TR NPC cells and in patient tumor tissues." (PMID 28277541, 2017). "Notably, the analysis of HAS3, ABCC5, SOX2 and CD133 tumor mRNA transcripts showed that Pa + 4Mu combination therapy significantly downregulated gene expression, as was observed in the previous in vitro assays (p < 0.01)." (PMID 39039104, 2024). "We identified some mutation markers specific to tumor types, including some typical tumor‐related genes (e.g., TP63, ABCC1, ABCC5, and TFDP1 in ESCA) as well as numerous noncoding genes (e.g., NPSR1‐AS1 and AC079466.1 in HCC) and pseudogenes (e.g., SDHAP3 and TPTEP1 in LUAD)." (PMID 38010945, 2024). "Moreover, the reduction of HAS3, ABCC5, and SOX2 gene expression induced by Pa + 4Mu, previously observed in vitro, was confirmed in tumor tissue from treated mice." (PMID 39039104, 2024). "Interestingly, PDE inhibitors were shown to inhibit several MDR transporters (e.g., ABCC4/MRP4, ABCC5/MRP5, ABCB1/P-gp, ABCG2/BCRP), thus enhancing chemotherapeutic drug accumulation in tumor cells and efficacy." (PMID 35008687, 2021). "ABCC5 is a prognostic marker for tumor progression and drug resistance, with low expression in normal hepatocytes but strong induction upon cellular damage from exogenous or endogenous agents, ABCC5 is crucial for drug absorption, distribution, metabolism, and excretion." (PMID 40860808, 2025). "The average expression level of the ABCA3 (p = 0.007), ABCB9 (p = 0.000), ABCC1 (p = 0.000), ABCC4 (p = 0.000), ABCC5 (p = 0.000), and ABCC6 (p = 0.000) genes was statistically significantly higher in patients without tumor cell infiltration in the lymph vessels." (PMID 36674773, 2023). "These tumor tissues were classified into two groups (positive + or negative –), and the positive tissues were further graded into four levels according to the degrees of FOXM1 or ABCC5 expression (negative, +, ++, +++)." (PMID 28277541, 2017).
infection (3 papers, 2013 to 2025). The state of being infected such as from the introduction of a foreign agent such as serum, vaccine, antigenic substance or organism. "qRT-PCR and western blotting were used to verify the efficiency of ABCC5 knockdown after lentiviral infection." (PMID 35504877, 2022).
bacterial infection (1 paper, 2021). "To investigate how bacterial infection impacts placental efflux transport potential, we investigated the expression of the of Abca1, Abcb1a, Abcb1b, Abcb4, Abcc2, Abcc5, Abcf2, Abcg1 and Abcg2 mRNAs in the mouse placenta at GD15.5 or GD18.5 following LPS challenge (4 h)." (PMID 34394055, 2021).
heart disease (1 paper, 2019). "ABCC5 was expressed in heart disease, but this gene may be associated with advancement of CAD." (PMID 31881747, 2019).